RNU7-47P (RNA, U7 small nuclear 47 pseudogene)
Synonyms: U7.47
Gene: Small nuclear RNA gene on chromosome 3 (142,801,207 to 142,801,268, forward strand). Ensembl gene ENSG00000251787.
Homologues: Orthologues: macaque U7 (94% identical). Paralogues in human: RNU7-3P (92% identical), RNU7-7P (92% identical), RNU7-11P (90% identical), RNU7-25P (90% identical), RNU7-13P (87% identical), RNU7-14P (87% identical), RNU7-22P (87% identical), RNU7-28P (87% identical), RNU7-4P (87% identical), RNU7-6P (87% identical), RNU7-8P (87% identical), RNU7-10P (85% identical), and 143 more.